POLD1 (DNA polymerase delta 1, catalytic subunit)
Diseases named in the same sentence as POLD1 in open-access papers (continued):
Sharing a sentence is not in itself a finding about the gene and the disease.
breast carcinoma (29 papers, 2016 to 2026). "Prospective data collection is needed to further clarify if the POLD1 DEDD domain altering allele increases the frequency of breast cancer development." (PMID 38067377, 2023). "On balance, colorectal, endometrial, and breast cancers were found in patients with germline POLD1 polymorphisms causing discordant AA substitution in the DEDD motif." (PMID 38067377, 2023). "Six of 43 (14%) female POLE variant heterozygotes developed breast cancer (median age 49 years, range 38–65), as did 4/17 (24%) female POLD1 variant heterozygotes (median age 62 years, range 52–65)." (PMID 33948826, 2022). "Given that breast cancer is the most common cancer in women, the co-occurrence of the POLD1 germline variant and breast cancer development may be incidental." (PMID 38067377, 2023). "The association of POLD1 exonuclease deficiency and breast cancer is unclear at this time." (PMID 38067377, 2023). "Previous studies have shown that POLD1 may be associated with the malignant proliferation of tumor cells and that a high expression of POLD1 is associated with the poor prognosis of breast cancer." (PMID 33747905, 2021). "The top three genes (WDR62, CDT1 and MCM2) positively correlated with POLD1 expression play important roles in cell proliferation and apoptosis, and their upregulation has been proved to be associated with tumors development and worse prognosis, such as breast cancer and lung adenocarcinoma." (PMID 35189839, 2022). "POLD1 downregulation suppressed cell proliferation and cell cycle progression in breast cancer cells." (PMID 33499187, 2021). "Overexpression of POLD1 has previously been linked to poor prognosis in hepatocellular and breast cancer; however, no study has previously related POLD1 expression to survival in ACC." (PMID 38935991, 2024). "In breast cancer, the high expression of POLD1 is closely related to poor prognosis." (PMID 37105989, 2023). "In addition, SIRT1 can affect the invasion and migration of breast cancer cells by upregulating POLD1 expression." (PMID 37105989, 2023). "For example, POLD1 is overexpressed in hepatocellular carcinoma and breast cancer, which predicts poor prognosis in patients, suggesting that POLD1 may be a potential prognostic marker and promising therapeutic target in cancers." (PMID 36119494, 2022). "Resveratrol (RSV) is known to possess anticancer properties in many types of cancers like breast cancer, in which POLD1 may serve as a potential target." (PMID 33747905, 2021). "POLD1 is the top predicted gene for breast cancer by GenePANDA." (PMID 28252032, 2017). "For some genes, single P/LP variants were detected either only in the group of patients with breast cancer (APC, MDM1, MRE11, POLD1, NF1, RAD51C, RECQL4, and WRN) or only in the control group (MCPH1, MSH3, and XPC)." (PMID 39684352, 2024). "In order to prove the anti-tumor effect of Diazinon in BC, we used it to treat breast cancer cells and observed that it increased the expression of TAT while suppressing the expression of CDC6, RPA3, POLD1, and POLD2." (PMID 39334853, 2024). "Similarly, apoptosis of triple-negative breast cancer (BC) cells was driven by the reduction in POLD1 expression." (PMID 36980791, 2023). "Previous studies suggested that POLD1 was upregulated in HCC and breast cancer, and its overexpression correlated with tumor progression and poor prognosis." (PMID 35189839, 2022). "Whilst this is based on only 40 female POLE ED heterozygotes and 17 female POLD1 heterozygotes, we conclude that female POLD1 ED heterozygotes in particular may be at an increased risk of developing breast cancer compared to the general population, but this is not proven." (PMID 33948826, 2022). "Subsequently, via ectopic expression of POLD1, the role of POLD1 in RSV-mediated breast cancer cell apoptosis in vivo and in vitro were further explored." (PMID 33747905, 2021).
breast carcinoma (continued). "This also revealed that the sex- or gender-specific cancer's (such as ovarian and breast cancers that are common among females) survival percentage is not influenced by POLD1 deregulation." (PMID 35620275, 2022). "High expression of Ki-67 serves as a marker for poor prognosis in breast cancer, and the obtained results demonstrated that RSV can inhibit the growth of TNBC cells and promote necrosis in cancer cells in vivo but was limited in the overexpression of POLD1." (PMID 33747905, 2021).
polyposis (24 papers, 2014 to 2025). "Here we studied an extended family with multiple members heterozygous for the pathogenic POLD1 variant c.1421T>C p.(Leu474Pro), which segregates with the polyposis and cancer phenotypes." (PMID 38658779, 2024). "Germline missense PV affecting proofreading capabilities of POLE/POLD1 are associated with increased EC risk as a part of polymerase proofreading-associated polyposis, but the importance of germline POLD1/POLE truncating variants remains rather elusive." (PMID 37153042, 2023). "It is worth mentioning that we previously evaluated the prevalence of the recurrent mutations POLE c.1270C>G, p.(Leu424Val) and POLD1 c.1433G>A, p.(Ser478Asn) in a cohort of Dutch index patients with multiple polyps or familial CRC." (PMID 30827058, 2019). "Recently, pathogenic variants in the POLE and POLD1 gene were found to explain a small portion of polyposis cases." (PMID 25604157, 2015). "Variants in the exonuclease domain of the polymerase proofreading genes POLE and POLD1 cause polymerase proofreading-associated polyposis, which is a dominant-inheritance and high-penetrance hereditary syndrome conferring a predisposition to attenuated colorectal polyposis and early-onset CRC." (PMID 32973888, 2020). "Moreover, mutations in polymerase proofreading–associated syndrome involving POLE and POLD1 constitute 0.3–0.7% of familial cancer cases when only CRC and polyposis are considered." (PMID 35751785, 2022). "However, it is remarkable that through all NGS efforts, only few novel high-penetrant risk genes for hCRC and polyposis have been established in the past decade, such as POLE, POLD1 and NTHL1." (PMID 33228212, 2020). "This is the youngest reported cancer patient with polymerase proofreading-associated polyposis indicating that POLE mutation p.(Val411Leu) may confer a more severe phenotype than previously reported POLE and POLD1 germline mutations." (PMID 27573199, 2017). "A few polyposis patients have been linked to other genes, such as SMAD4, BMPR1A, POLE and POLD1." (PMID 25604157, 2015). "Unlike APC and MUTYH polyposis, POLD1/POLE syndrome is characterized by the development of extraintestinal tumors, including endometrial, ovarian, brain, and pancreatic cancers." (PMID 39661238, 2025). "We identified no pathogenic variants in more recently discovered polyposis predisposition genes (POLE, POLD1 or NTHL1), rendering the presence of such founder variants rare." (PMID 39516274, 2024). "Here, we describe two teenage siblings with polyposis and CRC in whom we initially suspected CMMRD but found a novel digenic CPS caused by heterozygous germline PVs in PMS2 and POLD1." (PMID 36291559, 2022). "Recent studies have proposed the term “POLE/POLD1-associated tumor syndrome” to encompass a broader clinical spectrum beyond classical PPAP, recognizing that some patients carrying germline mutations in POLE or POLD1 may develop tumors without evidence of polyposis." (PMID 40661943, 2025).
colon cancer (17 papers, 2016 to 2025). "POLD1 plays an important role in human body and POLD1 mutation can raise the possibility of colon polyps and colon cancer in both men and women." (PMID 35620275, 2022). "Interestingly, we studied an MMR-proficient colon cancer (location: sigmoid colon) diagnosed in a 74-year-old patient with a constitutional POLD1 D402N variant, who had undergone resection of 42 colorectal polyps." (PMID 38658779, 2024). "Of the three patients other than our patient, one was diagnosed with GPV in POLE, and two were diagnosed with GPVs in POLD1; all of them had a history of colon cancer." (PMID 40741356, 2025). "Among MMR-associated genes, MSH6 and PMS2 were significantly more frequently mutated in CDX2-suppressed colon cancers, and the same was true for mutations in the proofreading polymerases POLE and POLD1 genes." (PMID 39452477, 2024). "Mutations in KIAA1217, POLD1, PIEZO1, NBEAL2, DDX17, and PARP14 were significantly more prevalent in patients with colon cancer and PRShigh than in those with PRSlow." (PMID 38577604, 2024). "Five of those (and three of the other colon cancer samples) have a nonsynonymous mutation in POLE and one of them in addition in POLD1, which encodes the DNA polymerase δ." (PMID 29673314, 2018). "Immunohistochemistry staining from HPA showed that POLD1 was highly increased in colon tumors." (PMID 36703617, 2023). "For the cancer susceptibility genes identified in the cohort that are not involved in LS, we found several genes implicated in the hereditary colorectal cancer landscape: APC, MUTYH, POLE, POLD1, and BLM, as well as genes resulting in an increased risk of colon cancer as CHEK2." (PMID 36232851, 2022). "POLD1 knockdown, iron chelation, and TFRC disruption increase DNA replication stress, DNA damage response, apoptosis, and reduce colon tumor growth." (PMID 36703617, 2023). "We compared the mutation spectrum of our aggregated HT115 branch variant SNV call set with mutation spectra derived from tumor-normal whole-genome sequencing of group A POLE colon tumors (samples with mutant POLE but not mutant POLD1) generated by the TCGA Research Network and found high similarity." (PMID 30459213, 2018).
lipodystrophy (15 papers, 2017 to 2026). A congenital or acquired disorder characterized by abnormal loss or redistribution of the adipose tissue in the body. "Mandibular hypoplasia, deafness, progeroid features, and lipodystrophy (MDPL) syndrome is a rare, autosomal dominant, inherited form of lipodystrophy caused by a mutation in the POLD1 gene, associated with multisystemic features." (PMID 40718185, 2025). "Reinier and co-workers also described a patient harboring the c.1812-1814delCTC (p.Ser605del) pathogenic variant in the POLD1 gene who had severe lipodystrophy and progeroid features." (PMID 36354755, 2022). "A multisystem disease characterized by mandibular hypoplasia, deafness, progeroid features, and lipodystrophy (MDPL) was associated with pathogenic variants in the POLD1 gene in seven patients." (PMID 36354755, 2022). "Mutation in DNA polymerase delta (POLD1) leads to lipodystrophy with a progressive loss of subcutaneous fat." (PMID 28273089, 2017). "This lipodystrophy occurs due to a mutation in the POLD1 gene (DNA polymerase delta 1)." (PMID 35356184, 2022). "Likewise, reduced subcutaneous fat in PRIM1-deficient individuals parallels the lipodystrophy found in POLD1 cases (who had normal growth) due to heterozygous single-codon deletion of the catalytic site of Pol δ." (PMID 33060134, 2020). "Mandibular hypoplasia, Deafness and Progeroid features with concomitant Lipodystrophy is a rare, genetic, premature aging disease named MDPL Syndrome, due to almost always a de novo variant in POLD1 gene, encoding the DNA polymerase δ." (PMID 35196257, 2022). "These de novo mutations in the POLD1 gene also result in autosomal dominant MDPL syndrome (mandibular hypoplasia, deafness, progeroid features, and lipodystrophy)." (PMID 35620275, 2022). "Mandibular hypoplasia, Deafness and Progeroid features with concomitant Lipodystrophy define a rare systemic disorder, named MDPL Syndrome, due to almost always a de novo variant in POLD1 gene, encoding the DNA polymerase δ." (PMID 33618333, 2021). "Among these, Mandibular hypoplasia, Deafness and Progeroid features with concomitant Lipodystrophy (MDPL; OMIM #615381) is a rare autosomal dominant disease due to a de novo in-frame deletion in POLD1 gene, encoding the catalytic subunit of DNA polymerase delta." (PMID 39611849, 2024). "Some studies have shown that POLD1 gene mutation and expression were associated with the pathogenesis of Werner syndrome and MDPL (mandibular hypoplasia, deafness, progeroid features, and lipodystrophy) syndrome." (PMID 33692996, 2021).
brain tumors (14 papers, 2014 to 2026). "CMMRD high grade brain tumours are often (ultra-)hypermutated due to somatic POLE or POLD1 exonuclease domain variants that impair polymerase proofreading, leading to a complete loss of replication error repair." (PMID 38789506, 2024). "In line with our findings, a recent report summarizing 132 carriers of probably pathogenic POLE/POLD1 germline exonuclease domain variants identified 10 (8%) brain tumor cases among these patients." (PMID 37990341, 2023). "At least two brain tumors were observed in six of the 10 (60%) families with rare POLE or POLD1 germline variants." (PMID 37990341, 2023). "Six of 10 (60%) families carrying POLE/POLD1 variants had at least two family members with brain tumors, with gliomas occurring together with meningiomas in two families." (PMID 37990341, 2023). "In our summary of 37 brain tumor patients carrying rare POLE/POLD1 germline variants, oligodendrogliomas were found in as many as 13.5% of cases." (PMID 37990341, 2023). "Nine patients with POLE pathogenic variants and one with a POLD1 pathogenic variant developed brain tumours." (PMID 33948826, 2022). "Thus, the brain tumors in POLE/POLD1 variant carriers with a definitive diagnosis were gliomas or medulloblastomas." (PMID 37990341, 2023). "Therefore, the analysis of POLE and POLD1 genes in the brain tumor DNA sample from patient III-2 revealed the presence of four variants in POLD1." (PMID 33924881, 2021). "Of note, concurrent MMRD and PPD is seen in the majority of CMMRD-associated malignant brain tumors and approximately one third of CMMRD-associated gastrointestinal cancers, due to the biallelic germline MMR PV along with somatic POLE/POLD1 PV." (PMID 39031223, 2024). "Cumulative incidence curves show the age-dependent penetrance of the following phenotypes in those heterozygous for a probably pathogenic POLE and POLD1 ED variant: CRC; colorectal adenoma(s); EC; and any cancer including brain tumour." (PMID 33948826, 2022). "Brain tumours (two astrocytomas at age 26) were observed in one of the first POLD1 Ser478Asn heterozygotes described." (PMID 33948826, 2022). "Another possible option that would allow the identification of CMMRD in brain tumors would be sequencing to determine MSI, mutation burden and signatures, and other alterations characteristic of these tumors, such as POLE or POLD1 variants." (PMID 33924881, 2021). "Pathogenic variants in POLE or POLD1 causing defective polymerase proofreading, and pathogenic variants in MMR genes causing defects in MMR can lead to a high TMB, i.e. hypermutation, in the DNA of human tumors, including brain tumors, when they occur in the germline or somatically." (PMID 37990341, 2023). "However, brain tumor surveillance may be considered in all (adult) patients with digenic inheritance of an MMR gene PV and POLD1 or POLE PV, as high-grade gliomas have been found in patients with LS and PPAP." (PMID 36291559, 2022).
colorectal adenoma (14 papers, 2013 to 2024). An adenoma that arises from the colon or rectum. "A decade ago, germline variants in the proofreading domain of POLE and POLD1 were found to predispose to colorectal adenomas and carcinomas, defining a new tumor syndrome, polymerase proofreading-associated polyposis (PPAP)." (PMID 37990341, 2023). "Germline mutations affecting the exonuclease domains of POLE and POLD1 predispose to colorectal adenomas and carcinoma." (PMID 30827058, 2019). "Specific germline mutations in the proofreading domain of POLD1 have recently been identified as underlying rare cause of multiple colorectal adenomas and carcinomas." (PMID 30680046, 2019). "There are also some reports of WGS being successfully used to implicate rare, high-penetrance germline variants in cancer, for example POT1 mutations in familial melanoma and POLE and POLD1 mutations in colorectal adenomas and carcinomas." (PMID 31614935, 2019). "The recently discovered germ-line mutations in POLE and POLD1 genes from individuals with multiple colorectal adenomas, carcinoma, or both are excellent examples in support of above assumption." (PMID 31226964, 2019). "We have recently shown that germline exonuclease domain mutations (EDMs) of POLE and POLD1 confer a high risk of multiple colorectal adenomas and carcinoma (CRC)." (PMID 23447401, 2013). "There are several reports of WGS being successfully implemented to implicate rare, high-penetrance germline variants in cancer, for example POT1 mutations in familial melanoma and Hodgkin lymphoma and POLE and POLD1 mutations in colorectal adenomas or carcinomas." (PMID 32211398, 2020). "Crypt-like structures from six colorectal adenomas and one carcinoma from individuals with germline POLE or POLD1 mutations were also microdissected and sequenced." (PMID 34594041, 2021). "As reported by previous studies, the POLE p.Leu424Val mutation frequency in multiple colorectal adenomas or familial CRC cohorts seems to be typically ≤ 0.3%, whereas the POLD1 p.Ser478Asn mutation seems to be even less frequent (< 0.1%)." (PMID 28423643, 2017). "We recently identified specific germline EDMs in POLD1 and POLE that are causative for the development of multiple colorectal adenomas and CRC." (PMID 24583393, 2014). "Recently, we identified germline exonuclease domain mutations (EDMs) in human POLD1 and POLE that predispose to ‘polymerase proofreading associated polyposis’ (PPAP), a disease characterised by multiple colorectal adenomas and carcinoma, with high penetrance and dominant inheritance." (PMID 24583393, 2014).